IL6 (interleukin 6)
Diseases named in the same sentence as IL6 in open-access papers (continued):
Sharing a sentence is not in itself a finding about the gene and the disease.
Sepsis (continued). "Research is ongoing to further evaluate the clinical significance of IL-6 and its incorporation into sepsis management guidelines." (PMID 39201697, 2024). "Our study highlights sTREM-1 as a valuable biomarker for predicting sepsis severity and progression, as evidenced by its strong correlation with APACHE II scores and its association with other key markers, such as IL-6 and lactate." (PMID 39655134, 2024). "IL-6 has been found to be elevated in several pathological circumstances, such as severe bacterial infections, sepsis, and in a variety of autoimmune diseases." (PMID 38409170, 2024). "Of the biomarkers assayed in our study, IL-6 has been most consistently identified as a promising sepsis biomarker in previous studies, though with variable sensitivity and specificity." (PMID 38312920, 2024). "Recent research suggests that IL-6 can independently predict the diagnosis of sepsis, with a sensitivity of 68%, a specificity of 83%, and an AUC of 0.764." (PMID 39201697, 2024). "Research has shown that IL-6 is closely linked to severity scores such as APACHE II and SOFA, serving as a critical indicator of poor outcomes in sepsis." (PMID 39655134, 2024). "In the retrospective study, stored plasma samples from 80 patients with severe sepsis were used to measure cfDNA, IL-6, thrombin, and protein." (PMID 38790893, 2024). "All of the cases in this study showed elevated IL-6 levels, with a 100% sensitivity for diagnosing sepsis, as reported in earlier studies." (PMID 39589972, 2024). "We found that homozygous and heterozygous Shank3 deficiency, but not Shank2 and Trpv1 deficiency, aggravates hypothermia, systemic inflammation (serum IL-6 levels), and sepsis mortality in mice, induced by lipopolysaccharide (LPS)." (PMID 36845137, 2023). "Although this mechanism has been investigated in the context of malignancy and metastasis, the same principle applies to the influence of IL-6 on pro-inflammatory pathways during infection and sepsis." (PMID 38138084, 2023). "Consistent with our previous findings, sepsis also induced a marked elevation of blood levels of G-CSF, IL-6, KC, and sTNFR1 at 24 h post CLP." (PMID 37239992, 2023). "Their findings support the consideration of IL-6 inhibition in randomised controlled trials in sepsis." (PMID 37686271, 2023). "In other murine models and clinical cases of sepsis, the serum upregulation of IL-6, TNFα, and HMGB1 was observed." (PMID 37569277, 2023). "Of note, the sepsis biomarkers IL-6, PCT, presepsin and CRP are released from various other non-neutrophil immune cells." (PMID 37324133, 2023). "We further analyzed the area under ROC curve of disease severity score (SOFA score, APACHE II score), peripheral blood AQP4, and inflammatory factors such as TNF‐α, IL‐6, and IL‐1β of sepsis along with SAE patients." (PMID 36922751, 2023). "Another study reported that the prognostic value of IL-6 levels for 28-day sepsis mortality increased over time, up to 7 days." (PMID 36383295, 2023). "It activates MyD88 then NF‐κB and finally releases inflammatory cytokines including TNF‐α, interleukin‐1β (IL‐1β), and IL‐6 which play crucial roles in occurrence and development of sepsis." (PMID 38455195, 2023). "IL-6 and IL-1α are important mediators of the acute-phase response and are released in the event of sepsis, ischemic injury, or toxicity." (PMID 36993800, 2023). "In sepsis, inflammatory cytokines, such as interleukin‐6 (IL‐6), IL‐1β, tumour necrosis factor (TNF), and the acute phase protein, serum amyloid A1 (SAA1), are increased in serum and skeletal muscle of patients and mice." (PMID 37209006, 2023). "Among these, major pro-inflammatory cytokines, interleukin-6 (IL-6) reflects sepsis at the acute stage." (PMID 36383295, 2023). "For instance, substantial single pass IL-6 elimination has been described both in a pig model of severe smoke and burn injury, as well as in 100 mechanically ventilated sepsis patients." (PMID 36945034, 2023).
Sepsis (continued). "Sepsis triggers a systemic inflammatory response, releasing endotoxins such as lipopolysaccharide (LPS) and proinflammatory cytokines such as IL-6, IL-1 β, NO, and ROS." (PMID 37009158, 2023). "The present study was established to preliminarily develop a novel simple prediction model for the prognosis of 28-day mortality of sepsis by combining the predictive performance of the levels and clearance of IL-6, LAC, and PCT." (PMID 36383295, 2023). "The concentrations of the proteins S100A8, MMP8, CSF3, and IL-6, were measured in peripheral blood samples from 31 sepsis patients to validate the critical extracellular proteins identified in the study." (PMID 37901226, 2023). "Prior studies have shown that serum OPN levels are high in systemic inflammatory response syndrome (SIRS) and severe sepsis/septic shock and correlate with levels of interleukin 6 (IL-6)." (PMID 37371722, 2023). "In this article, sepsis dramatically increased the levels of the inflammatory cytokines IL-1β, IL-6, and TNF-α, although this rise was reduced following PTP treatment." (PMID 37361224, 2023). "EA and Acu-exo reduced the W/D and lung tissue damage in sepsis mice, down-regulated the expression of serum inflammatory cytokines TNF-α and IL-6, and increased the survival rate of sepsis mice." (PMID 37635258, 2023). "Consistently, a recent study showed that levels of C-reactive protein (CRP), TNF-α, and IL-6 decreased significantly after CRRT in patients with sepsis-induced acute kidney injury (AKI)." (PMID 36650427, 2023). "One of the most significant biomarkers of sepsis is the proinflammatory cytokines IL-6 and TNF-α, which are closely related to patient outcomes." (PMID 37293234, 2023). "IL-6 is an important contributor to the pro-inflammatory response to infections that remains elevated up to 32-h of sepsis." (PMID 37535121, 2023). "A role for histone modification was shown in a mouse model of sepsis, and treatment with histone deacetylase inhibitors appeared beneficial in improving lung injury, survival, and the level of circulating Il-6 in the blood." (PMID 36769095, 2023). "This makes serum IL-6 the most accurate and first laboratory parameter to rise in cases of sepsis after the first week of life." (PMID 36216867, 2023). "IL-6 concentrations exhibit their peak levels on the first day of neonatal sepsis, demonstrating a marked sensitivity within the initial hours of infection." (PMID 38255366, 2023). "We found that Daph obviously protected animals from mortality, reduced the LPS-induced alveolar edema and inflammation cells infiltration in sepsis mice, and suppressed the production of pro-inflammatory factors including IL-1β, IL-18, IL-6, TNF-α and iNOS." (PMID 36998049, 2023). "During sepsis, IL-6 levels rise rapidly after TNF-α and IL-1 concentrations and play a vital role in the patient’s progression to multiorgan failure." (PMID 38275661, 2023). "We also performed ELISA to assay the expression of inflammatory cytokines, and results revealed that the concentrations of TNF‐α, IL‐1β, and IL‐6 were notably increased in the sepsis cell model (p < .001)." (PMID 37647440, 2023). "In agreement, other studies have reported lower plasma concentrations of TNF-α and IL-6 in transgenic mice expressing CETP compared to wild-types following LPS stimulation or sepsis." (PMID 37892238, 2023). "Treatment with Tretinoin in sepsis will inhibit the activation of NF-κB and related target genes such as IL-6, MCP-1 and COX-2." (PMID 37700323, 2023). "In a randomised trial involving patients with sepsis-associated AKI, CRRT with oXiris was associated with decreased endotoxin, TNF-alpha, and IL-6 levels as compared to CRRT using a standard high-flux haemodiafilter." (PMID 36750878, 2023). "In the current study, we report for the first-time serum IL-6 cut-off values for the diagnosis of sepsis in neonates and preterm infants stratified for day of life." (PMID 36216867, 2023).
Sepsis (continued). "PSP has been reported to have a higher diagnostic performance in identifying sepsis than other established biomarkers such as procalcitonin (PCT), interleukin 6 (IL-6), and C-reactive protein (CRP)." (PMID 37176638, 2023). "In this study, we found that PT pretreatment significantly reduced the levels of serum TNF-α, IL-1β, and IL-6 induced by sepsis." (PMID 38152336, 2023). "Sepsis is characterised by dysregulated, life-threatening immune responses, which are thought to be driven by cytokines such as interleukin 6 (IL-6)." (PMID 36716318, 2023). "Plasma IL-6 levels at the three time points were higher in the sepsis group than in the control group (P < 0.01)." (PMID 37533741, 2023). "In the cecal ligation and puncture (CLP)-induced sepsis model, the number of CX3CR1+CCR2-CD64+CRMs begins to decrease from the first day of sepsis, which is associated with TNF-α and IL-6 signaling and leukocyte infiltration." (PMID 38027963, 2023). "ApoE23 treatment dramatically decreased plasma TNF-α and IL-6 levels at the three time points compared to those in the sepsis group." (PMID 37533741, 2023). "In our SIRS/sepsis cohort, the plasma sCD137 positively correlated with procalcitonin (r = 0.186, p = 0.024) and IL-6 (r = 0.181, p = 0.029), and negatively with CRP (r = −0.187, p = 0.022)." (PMID 38139346, 2023). "Correlation between the levels of PCT and IL-6 cell subsets and the recovery of different sepsis (χ̅±S) n=40." (PMID 36694784, 2023). "In this study, IL-6 levels were measured consecutively for 72 h from admission, and IL-6 clearance was calculated on D3 (48–72 h) to assess the prognostic value of IL-6 in sepsis." (PMID 36383295, 2023). "This kinetic variation underscores the rapid turnover of IL-6, with a short half-life, rendering it highly responsive on the first day but progressively less on subsequent days of sepsis." (PMID 38255366, 2023). "In concert with trial, registry, and MR data supporting the causal effect of altering IL-6 pathway activity on infection, these data support the view that observed HDL associations with sepsis are—in part—downstream of IL-6 signalling." (PMID 37814277, 2023). "Second, we serially measured the concentrations of three potential biomarkers of sepsis, including IL-6, LAC and PCT." (PMID 36383295, 2023). "Although these IL6 levels are remarkably high as compared to patients with sepsis (<1 ng/ml) or septic shock (up to 10 ng/ml), they suggest a critical role of IL6 in lethal endotoxemia." (PMID 37520526, 2023). "We next looked for evidence of acute systemic sepsis by measuring serum concentrations of the pro-inflammatory cytokines IL-6 and TNFα in mice." (PMID 37681974, 2023). "CLP—sepsis induced an acute increase in both inflammatory (IL-6 and MCP1) and anti-inflammatory (IL-10) serum cytokine concentrations." (PMID 37696985, 2023). "In a mouse model of sepsis, the serum level of interleukin-6 significantly decreased, and the rectal temperature of mice was recovered in the inotodiol emulsion group, indicating that inotodiol microemulsion is an effective oral delivery method." (PMID 36830005, 2023). "Another study suggested that MALAT1 depletion is responsible for the sepsis inflammatory response by inhibiting the expression of IL-6 and TNF-α and the NF-κB signaling pathway by upregulating miR-150-5p." (PMID 37109540, 2023). "For example, Qiu and colleagues reported cutoff levels of IL-6 for the diagnosis of sepsis in moderately preterm infants in the context of premature rupture of membranes, yet they did not extrapolate to uncomplicated births or other maternal morbidities." (PMID 37606448, 2023). "We aimed to search for a novel 28-day sepsis mortality prediction model based on serial interleukin-6 (IL-6), lactate (LAC), and procalcitonin (PCT) measurements." (PMID 36383295, 2023). "Within the limitations and assumptions of MR, these findings support the consideration of IL-6 inhibition in randomised controlled trials in sepsis." (PMID 36716318, 2023).
Sepsis (continued). "One day after sepsis induction, all animals presented peritonitis with bacterial infection as well as elevated C-reactive protein, haptoglobin, IL-1Ra, IL-6, and IL-1b." (PMID 38087374, 2023). "Interleukin (IL)-1β, tumour necrosis factor (TNFα), high mobility group protein 1 (HMGB1) and IL-6 are the most vital cytokines promoting the inflammatory response in sepsis and are key biomarkers of septic shock in systemic inflammatory response syndrome." (PMID 37474902, 2023). "High levels of interleukin-6 (IL-6) is one of the hallmarks of sepsis and augments the production of reactive oxygen species (ROS), compromising deiodinase function and altering the peripheral T3/T4 activation/inactivation process." (PMID 36835345, 2023). "In summary, our work demonstrates that P2X7 expression is highly induced in lymphocytes during sepsis, and this correlates with IL-18, along with other inflammatory mediators such as IL-6, IL-8, and procalcitonin." (PMID 38094297, 2023). "Meanwhile, the cytokine levels in the plasma of rat including IL‐17A, TNF, and IL‐6, the critical factors for the disorder of immune system and high mortality in sepsis model, were measured by flow cytometry analysis." (PMID 38023725, 2023). "Serum IL-6 starts highly elevated in cases of culture-confirmed sepsis on DOL 1, whereas CRP takes 48 h to reach its peak." (PMID 36216867, 2023). "The aim of this study was to determine optimal cut-off values for serum IL-6 in diagnosing culture-confirmed sepsis in neonates and very-preterm (VP, born before 32 weeks of gestation) and VLBW infants." (PMID 36216867, 2023). "IL-6 is another important inflammatory cytokine and IL-6 mRNA was demonstrated that in lung with sepsis and serum IL-6 is a candidate marker for sepsis." (PMID 37494665, 2023). "Patients with sepsis had increased serum levels of IL-6, IL-10, IFN-γ, and neutrophil HSP90α expression compared to controls but repressed monocyte HSP90α." (PMID 36615909, 2023). "Among the tested sepsis biomarkers, IL-6 levels were most significantly correlated with NE-SFL (r = 0.57; p < 0.001) and NE-WY (r = 0.68; p < 0.001), followed by PCT (r = 0.56 and r = 0.59) and presepsin (r = 0.30 and r = 0.38, respectively)." (PMID 37324133, 2023). "Once the assay is optimized, trialswith patient blood samples can be carried out to compare performanceto other IL-6 LFDs in the detection of sepsis." (PMID 36910974, 2023). "Interleukin-6 (IL-6) is highly associated with CRS severity and can be useful when attempting to differentiate between CAR-T-related CRS and CRS related to sepsis." (PMID 37623035, 2023). "We first assessed the therapeutic applicability of Gp130 exon 9 SSOs in an LPS-induced inflammation model in mice, which clinically mimics sepsis and where IL-6 plays a critical role in the pathophysiology." (PMID 37759507, 2023). "It was found that the G/A gene polymorphism of TNF-α-308 is significantly positively associated with a higher incidence of sepsis and increased expression of cytokines such as TNF-α, IL-6, and IL-8 in patients." (PMID 37753078, 2023). "Knockdown of TRAF6 also resulted in decreased mRNA expression of Tnfα and Il-6 in Sufu-cKO mice induced with LPS, suggesting that Sufu suppressed lung inflammation during sepsis via interfering TRAF6 function." (PMID 37441604, 2023). "The study found significantly higher levels of pro-inflammatory cytokines (TNFa, IL1B, and IL-6) in the lung tissue of the sepsis and vehicle groups compared to the sham group." (PMID 37675176, 2023). "They presented a sensing system that uses functionalized screen-printed electrodes (SPEs) and a heat-transfer method (HTM) to detect the presence of interleukin-6 (IL-6) in human blood plasma as a biomarker for sepsis detection." (PMID 37622890, 2023). "In the early stages of sepsis, a significant increase in IL-6 levels occurs as a surrogate marker of the pro-inflammatory response and is associated with increased intestinal permeability." (PMID 38287976, 2023).
Sepsis (continued). "In the acute setting, patients with sepsis secondary to infection had significantly elevated levels of IL-6." (PMID 37104297, 2023). "On the other hand, Prompt diagnosis is essential for IL-6-related diseases such as sepsis, where diagnosis and administration of specific therapy within the first 6 h of disease onset can significantly improve patient outcomes." (PMID 37754132, 2023). "As expected, the levels inflammatory cytokines TNF-α, IL-1β, IL-6 were increased in serum and lung in sepsis mice compared with control group." (PMID 37494665, 2023). "Consistently, the ELISAs of TNF-α, IL-1β and IL-6 showed that the serum TNF-α, IL-1β and IL-6 levels in the sepsis group were higher than those in the control group." (PMID 36544058, 2023). "Probably the best combination for early sepsis would be the use of PCR and IL-6 or IL-8 in an attempt to cover the earliest and later phases of the immune response." (PMID 36980160, 2023). "Mokart recently showed that IL-6 is a good independent early marker of postoperative sepsis, severe sepsis or septic shock after major oncological surgery." (PMID 38098074, 2023). "For example, in sepsis, cytokines such as IL-6, TNF-α, IL-1β, and CXCL8 increase antibody production, vascular permeability, and neutrophil recruitment." (PMID 37600769, 2023). "Elevated IL-6 levels were not only shown to correlate with the severity of sepsis but also to be highly predictive of adverse outcome following cardiac surgery." (PMID 37711559, 2023). "During the course of LPS sepsis (0–36 hpi), most PICCs reached the first and second peak at 6 and 16 hpi, respectively, with IL-6, IL-18, CCL5, CCL7 and CXCL1 sustaining at plateau at 36 hpi." (PMID 37332010, 2023). "In sepsis, these cytokines (IL-1α, IL-1β, IL-6, and TNFα) can be released in the blood and cross the BBB through their respective transporters." (PMID 37569277, 2023). "We demonstrate in a single-centre cohort of over 1500 neonates including over 700 VLBW infants and of those almost 400 ELBW infants, that serum IL-6 has a high accuracy for the diagnosis of culture-confirmed sepsis in this patient population." (PMID 36216867, 2023). "Patients with early mortality showed a significant positive correlation with elevated CRP (CRP >= 8 mg/L), higher IL-6, a medical history of sepsis, and intestinal infection." (PMID 37155023, 2023). "In this study, we provide evidence from multiple, independent data sources that blockade of IL-6 signalling pathways is likely to be protective against the development of sepsis." (PMID 36716318, 2023). "The inflammatory cascade is mainly initiated by IL-6 and IL-8, which have been demonstrated to be increased in the first 24 h after sepsis onset in both early onset sepsis (EOS) and late onset sepsis (LOS)." (PMID 36829980, 2023). "Then, we explored the inflammation responses during sepsis, where the serum levels of the inflammatory markers (IL-6 and TNF-α) were determined." (PMID 37512913, 2023). "Sepsis is an important cause of cytokine storm, involving increased TNF, IL-1β, and IL-6 production through proinflammatory cells and sepsis pathology." (PMID 37108210, 2023). "A previous study found that HIF-1α promoted the production of inflammatory cytokines from macrophages, including IL-6, IL-12p70, and IL-1 in LPS-induced sepsis." (PMID 37709757, 2023). "Interleukin 6 (IL-6) is a critical cytokine involved in the innate immune response in sepsis and other severe infections and contributes in conjunction with other pathophysiological processes to adverse outcomes." (PMID 36716318, 2023). "Studies comparing nCD64 with C reactive protein (CRP), procalcitonin (PCT), and other common biomarkers of sepsis including white blood cell (WBC) count and interleukin-6 (IL-6) have found a superior performance of nCD64 in early detecting sepsis." (PMID 37746077, 2023).